INS (insulin)
Diseases named in the same sentence as INS in open-access papers (continued):
Sharing a sentence is not in itself a finding about the gene and the disease.
vitamin D deficiency (continued). "Although metformin improved glucose homeostasis in all groups of postmenopausal women, the effect on glucose, insulin, HOMA1-IR, and HbA1c was more pronounced in individuals with normal vitamin D status than in subjects with vitamin D insufficiency." (PMID 37297909, 2023). "Among HF-increased serum levels of insulin, TG, TC, LDL-cholesterol, serum insulin, TC and LDL-cholesterol concentrations were exacerbated by vitamin D insufficiency." (PMID 28353634, 2017). "Vitamin D supplementation has been shown to increase insulin sensitivity and to decrease androgen levels in women with PCOS and vitamin D deficiency, but does not seem to have these effects in women without PCOS that have vitamin D deficiency." (PMID 35566720, 2022).
Sepsis (282 papers, 2004 to 2026). Sepsis is defined as life-threatening organ dysfunction caused by a dysregulated host response to infection. "While poor glycemic control is a known contributor to severe infections, certain antidiabetic treatments, including insulin, metformin, and thiazolidinediones, have been linked to a reduced incidence and mortality in sepsis." (PMID 40428822, 2025). "This longitudinal study found that insulin use was associated with a 2.6-fold increase in sepsis risk among patients with T2DM, even after adjusting for age, comorbidities, and lab markers." (PMID 40863575, 2025). "Insulin use was associated with a 2.6-fold increased sepsis risk (OR = 2.6, 95% CI: 2.09–3.34, p < 0.001), while SGLT2 inhibitors (OR = 0.56, 95% CI: 0.34–0.91, p = 0.02) and GLP-1 receptor agonists (OR = 0.39, 95% CI: 0.19–0.79, p = 0.009) were protective." (PMID 40863575, 2025). "Previous studies have demonstrated the inhibitory effect of insulin on the release of sepsis-associated cytokines, including IL-1, IL-6, and TNF-α." (PMID 39263577, 2024). "Another important finding of this work is that sepsis is associated with increased relaxation of aorta segments in response to insulin and that this effect is completely prevented by the treatment with the nutraceutical." (PMID 35795581, 2022). "In this review we will focus on the importance of the ICUAW-risk factors inflammation and sepsis, insulin resistance, feeding status and immobilization as well as muscle activation for the disease course." (PMID 35615361, 2022). "Progression of sepsis is associated with changes in insulin and cortisol circulating levels, resulting in significant glucose perturbations, organ damage and activation of the immune system." (PMID 33973089, 2021). "It has become widely accepted that insulin resistance and glucose hypermetabolism can be linked to acute pathologies, such as burn injury, severe trauma, or sepsis." (PMID 34575946, 2021). "Since then, it has become widely accepted that insulin resistance and glucose hypermetabolism can be linked to acute pathologies, such as burn injury, severe trauma, or sepsis." (PMID 34575946, 2021). "Patients with sepsis who are administered intensive insulin treatment also have a high risk of hypoglycemia and hyperglycemia." (PMID 34679496, 2021). "Approximately half of these episodes can be explained by an underlying illness, such as severe sepsis, renal failure, liver failure, or malignancy; however, the remaining half are iatrogenic in nature, usually resulting from insulin treatment." (PMID 34842544, 2021). "Age, admission from inpatient unit, sepsis, hydroelectrolyte imbalance, changes in glycemic index, tube feeding, mechanic ventilation, sedation with fentanyl, insulin use, and higher Charlson scores were associated with mortality in this study." (PMID 32802502, 2020). "Birth asphyxia was associated with lower serum insulin, while probable sepsis with relatively higher levels." (PMID 32637004, 2020). "Earlier studies reported that insulin treatment protects against multiple organ damages caused by sepsis and reduces mortality among critical patients." (PMID 29285858, 2018). "Here, we found levels of insulin and leptin, a hormone and an adipokine associated with metabolic (predominantly anabolic) and immune functions were lower in sepsis survivors." (PMID 29326685, 2017). "Persistent inflammation has been implicated, and it is proposed that insulin signaling contributes to persistent inflammatory signaling during the recovery phase after sepsis." (PMID 26791145, 2016). "In conclusion, the results presented here confirm and extend the finding that the lungs of diabetic rats are “protected” from secondary injury caused by sepsis and that insulin abolishes this “protection”." (PMID 25398720, 2014).
Sepsis (continued). "In these patients, the decrease in mortality recorded for the intensive insulin group was associated with a decrease in both the frequency of infections (46%) and in the number of deaths due to multiple organ failure of known sepsis origin." (PMID 18799004, 2008). "Intensive insulin therapy was provided a grade B recommendation for the treatment of patients with severe sepsis – a population of patients at much higher risk for death." (PMID 16280057, 2005). "SGLT-2 inhibitors and GLP-1 RAs may be preferred for older T2DM patients at elevated sepsis risk, while insulin-treated patients may benefit from closer infection monitoring." (PMID 40863575, 2025). "However, the relationship between insulin therapy and sepsis risk is complex and influenced by multiple factors." (PMID 40863575, 2025). "The sepsis and wound management associated with NSTIs trigger a metabolic response, driven by inflammatory and neuroendocrine changes, that leads to high circulating levels of cortisol, catecholamines, insulin, and pro-inflammatory cytokines." (PMID 40364198, 2025). "After adjusting cardiogenic shock, respiratory failure, SAPSII, SOFA, GCS, CCI, SPO2, platelet, total bilirubin, vasopressor, antibiotics, and insulin, albumin infusion was associated with decreased risk of sepsis in the AP patients (Model 2: adjusted OR=0.37, 95%CI = 0.13–0.88, P = 0.039)." (PMID 40773463, 2025). "Several studies highlight the fact that insulin may be associated with higher rates of infections, including sepsis, compared with other glucose-lowering agents." (PMID 40863575, 2025). "Severe infections may be facilitated by inadequate glycemic control as insulin and oral antihyperglycemic drugs have been associated with lower incidence of sepsis." (PMID 38535079, 2024). "Body weight was thought to be a relevant morphologic parameter, as it has been associated with the extent of pathological changes in sepsis related laminitis and suggested to account for the faster rate of laminitis onset in horses compared with ponies, when they are infused with insulin." (PMID 35042535, 2022). "Whereas a substantial proportion of severe infections can be attributed to poor glycemic control, treatment with insulin, metformin and thiazolidinediones may be associated with lower incidence and mortality for sepsis." (PMID 33973089, 2021). "Thus, an association between preadmission treatment with insulin or non-insulin glucose-lowering agents and the risk and outcome of sepsis remains controversial." (PMID 33973089, 2021). "Besides glucocorticoid and catecholamine effects, insulin resistance is thought to be caused mainly by pro-inflammatory cytokines in sepsis." (PMID 26873079, 2016). "Although sepsis is the chief cause of death in ICUs, whether the impact and safety of intensive insulin therapy in septic patients are the same as those in critically ill patients is uncertain." (PMID 25136614, 2014). "Is age, gender, type of surgery, severity of disease, severity of organ dysfunctions, application of steroids, adrenaline, noradrenaline, steroids or insulin, and severe sepsis and shock associated with blood glucose concentrations < 80 mg/dl or ≥ 150 mg/dl, respectively?" (PMID 21470423, 2011). "Contrary to our findings, some studies reported that a higher plasma level of HbA1c, independently predicting hospital mortality in diabetic patients with sepsis, was observed in patients with bloodstream infection and that the use of intensive insulin treatment might be the cause." (PMID 33344465, 2020). "Contrary to sepsis, where clinicians recommended minimal drugs, clinicians consistently administered insulin and/or OADs with a slightly higher preference for insulin." (PMID 39792998, 2026). "SIH is a common metabolic reaction in acute critical illness (such as sepsis), mediated by the release of stress hormones including epinephrine and cortisol, accompanied by insulin resistance and enhanced hepatic gluconeogenesis." (PMID 41585235, 2025).
Sepsis (continued). "DPP4 plays key roles in glucose and insulin metabolism, as well as immune regulation—processes highly relevant to sepsis." (PMID 40124361, 2025). "The guidelines of survival sepsis campaign and multiple studies have indicated that maintaining blood glucose levels between 80 and 100 mg/dl through continuous insulin infusion can lead to a decrease in ICU mortality among critically ill patients." (PMID 40225322, 2025). "Sepsis can further complicate the clinical scenario, enhancing insulin resistance and promoting ketoacidosis." (PMID 40741547, 2025). "In SSCG 2021, for adults with sepsis or septic shock, initiating insulin therapy at a glucose level of ≥ 180 mg/dL is recommended (Strong recommendation; moderate quality of evidence)." (PMID 38658435, 2024). "An increased concentration of inflammatory cytokines (TNF-a, IL-1, IL-6) under sepsis, or chronic inflammation conditions, inhibits insulin signaling through different mechanisms, including reduced TK activity and reduced insulin binding affinity." (PMID 38539988, 2024). "Insulin at a glucose level of 180 mg/dL or higher (10 mmol/L) in adult patients with sepsis or septic shock should be initiated." (PMID 38254870, 2024). "The links between immune activation and β-cell responses, between sepsis and insulin, and between β-cell stress and PSP are described." (PMID 39200255, 2024). "This is the first study to systematically examine how the interaction of insulin with glucose over the physiologic range affects the expression of a virulence factor known to play a role in sepsis." (PMID 37998031, 2023). "There is good evidence for the two 15-LOX metabolites of ALA, 9- and 13-HOTrE, to display anti-inflammatory and immunomodulatory effects in mice, reducing tissue inflammation and sepsis and improving insulin sensitivity." (PMID 37047085, 2023). "Cannula patency and placement should be checked, administration of intravenous insulin infusion at the correct rate should be confirmed, and the possibility of concomitant pathology, such as infection or sepsis, should also be considered." (PMID 37568965, 2023). "The authors indicated that insulin treatment increased the levels of inflammatory cytokines produced by macrophages in patients with lipopolysaccharide-induced sepsis." (PMID 37048638, 2023). "The prognosis of sepsis is closely tied to the severity of inflammatory responses, which are significantly correlated with insulin resistance." (PMID 37940931, 2023). "Ultimately, the complex endocrine/inflammatory milieu of sepsis makes it difficult to determine if direct insulin resistance is truly present." (PMID 37550630, 2023). "Since sepsis is associated with capsule formation, whether there is a correlation between biofilm formation and capsule production with respect to response to the insulin/glucose ratio for K. pneumoniae was examined using a highly stable encapsulated strain of K. pneumoniae ATCC 27736." (PMID 37998031, 2023). "Conversely, our demonstration that CLP attenuated IRS-1/2 tyrosine phosphorylation indicates that CLP, and perhaps sepsis, are indeed states of insulin resistance." (PMID 37550630, 2023). "The combination of early rises in cortisol, catecholamines, and glucagon during sepsis in conjunction with an initial decrease in insulin rapidly impacts upon bioenergetics and metabolic activity." (PMID 37144447, 2023). "During sepsis, the rapid changes in microvascular circulation in skeletal muscle have a serious hindrance to the delivery of insulin." (PMID 35045818, 2022). "Upon HHS and sepsis resolution, a basal-bolus insulin therapy was implemented that was followed by significant improvement of daily glucose profiles and progressive reduction of insulin requirement until complete discontinuation." (PMID 35295985, 2022). "Various treatments and auxiliary drugs, such as corticosteroids, insulin, and recombinant activated protein C have been used to treat sepsis." (PMID 36439878, 2022).
Sepsis (continued). "Alterations of glucose metabolism and insulin sensitivity have been comprehensively studied under proinflammatory conditions, while knowledge on the role of lipid metabolism in sepsis remains scarce." (PMID 36551906, 2022). "Some risk factors for ICUAW such as disease severity, inflammation and sepsis, insulin resistance, feeding status, and long-lasting mechanical ventilation have been identified but the molecular mechanisms are not well defined." (PMID 35615361, 2022). "In the early 2000s, randomized controlled trials showed the promising effects of insulin glycemic control in patients with sepsis." (PMID 34072402, 2021). "Our data demonstrated that exercise prominently increased serum insulin concentrations during sepsis." (PMID 34493741, 2021). "Insulin levels were in the low normal range upon presentation (opposite to glucagon) and the levels were normalized upon resolution of sepsis." (PMID 34659208, 2021). "Insulin treatment was demonstrated to increase macrophage-produced inflammatory cytokine levels in the context of lipopolysaccharide-induced sepsis." (PMID 34367067, 2021). "AE decreased the serum levels of lactate and HMGB1 but increased blood glucose levels and serum insulin levels during sepsis." (PMID 34493741, 2021). "Sepsis increases serum cortisol and inflammatory cytokine levels, which increase insulin resistance and gluconeogenesis." (PMID 34679496, 2021). "AE impaired HMGB1 release via decreasing lactate and Glut1 expression and increasing insulin expression during sepsis." (PMID 34493741, 2021). "In contrast, many studies have demonstrated that insulin treatment in the setting of sepsis is anti-inflammatory." (PMID 33992101, 2021). "In our study, levels of valine were lower with increasing sepsis severity, despite insulin resistance and protein degradation, with skeletal muscle wasting being a common feature of septic patients." (PMID 34578983, 2021). "The Volume Substitution and Insulin Therapy in Severe Sepsis (VISEP) study enrolled 480 severe sepsis patients who were randomized to tight glycaemic control or standard glucose control." (PMID 34220705, 2021). "A hyperglycemic response, which results from pronounced insulin resistance and altered glycogen metabolism, is often observed at the early stages of sepsis." (PMID 34361061, 2021). "The median (IQR) serum insulin level was significantly higher in babies with probable sepsis (k = 9.348, p = 0.025) compared with other groups of babies." (PMID 32637004, 2020). "Collectively, insulin potentially exerts anti-inflammatory effects and in turn alleviates pyroptosis in mice with LPS-induced sepsis." (PMID 33679687, 2020). "The median (IQR) serum insulin level among babies with probable sepsis was 24.0 (7.3-43.2) μIU/ml while the median (IQR) serum insulin level among babies with confirmed sepsis was 9.9 (3.5-34.0) μIU/ml." (PMID 32637004, 2020). "Currently, insulin therapy is a critical part of treatment for diabetic patients, particularly for those with severe sepsis or septic shock." (PMID 33344465, 2020). "The present study showed that serum insulin level in the babies with probable sepsis was significantly higher than that of the other groups of babies." (PMID 32637004, 2020). "For example, the administration of glucose insulin potassium solution in sepsis has been shown to beneficially influence both clinical outcome and morphological derangements of mitochondria in human liver cells." (PMID 31089886, 2019). "It is well known that infectious and inflammatory diseases such as sepsis and systemic inflammatory response syndrome are accompanied by metabolic alterations such as insulin resistance or dysregulated adipokines." (PMID 31083558, 2019). "Sepsis was included as an outcome between metformin and insulin by 4 studies which involved 1167 GDM patients." (PMID 31781670, 2019).